COL10A1 (collagen type X alpha 1 chain)
Diseases named in the same sentence as COL10A1 in open-access papers (continued):
Sharing a sentence is not in itself a finding about the gene and the disease.
lung carcinoma (15 papers, 2018 to 2025). "COL10A1 is secreted small-chain collagen in the extracellular matrix associated with various tumors, including gastric, colon, breast, and lung cancer." (PMID 37006317, 2023). "For instance, TMEM106B has been shown to be a valuable marker of lung cancer metastasis, whereas COL10A1 plays a diagnostic role of circulating extracellular matrix-related proteins." (PMID 31640282, 2019). "In lung cancer, COL10A1 expression is associated with tumor progression and metastasis." (PMID 41373732, 2025). "COL10A1 was highly expressed in the plasma in gastric, colon, breast, and lung cancer and might be a potential diagnostic predictor." (PMID 37006317, 2023). "As for lung adenocarcinoma, COL10A1 upregulation exhibited positive relation to lymph node metastasis, and COL10A1 was treated as a novel target specific to lung cancer." (PMID 36276283, 2022). "Using the COL10A1 as a candidate biomarker, the occurrence of early cancer in gastric, colon, breast and lung cancer can be identified by serum detection." (PMID 33371777, 2021). "Each fibroblast type expresses a unique repertoire of collagens and other extracellular matrix components, and COL10A1 is the specific high-expressing collagen of cluster 1 in lung carcinoma." (PMID 33324550, 2020). "Thus, COL10A1 upregulation promotes cell proliferation and metastasis and inhibits apoptosis and autophagy in lung cancer cells." (PMID 41303526, 2025). "Moreover, a research confirmed that the expression of circulating protein COL10A1 was substantially elevated in the plasma of lung cancer patients compared with lung cancer cells." (PMID 36246404, 2022). "However, COL10A1 was detected highly expressed in the plasma of lung cancer patients, the role of COL10A1 in the progression of lung adenocarcinoma is not clear." (PMID 33324550, 2020). "Our data suggest however that COL10A1 could represent a potentially promising biomarker for lung cancer in females and that its relevance could be potentially explored in gender-related cancers such as breast or ovarian or in specific subgroups in other cancers." (PMID 30227835, 2018). "By intersecting these top DEGs, we recognized seven genes potentially involved in the pathogenesis of both SSc and lung cancer: SCN7A, AGTR1, WIF1, PRKG2, LTF, AQP4, and COL10A1." (PMID 39744538, 2024). "Note, in the human lung upregulation of COL10A1 is part of the ECM remodeling, especially in lung cancer patients, and this collagen stimulates cell proliferation." (PMID 37932771, 2023). "Adequate findings on COL10A1 and NQO1 in lung cancer have been reported; therefore, HS6ST2 was identified as our gene of interest." (PMID 35260044, 2022). "The levels of COL10A1 and SPARC were significantly higher in lung cancer patients compared to healthy controls." (PMID 33066583, 2020). "Plasma samples from lung cancer patients and healthy heavy-smokers controls were tested for levels of COL11A1 and COL10A1 (n = 57 each) and SPARC (n = 90 each)." (PMID 30227835, 2018). "To demonstrate the potential clinical utility of ECM-related proteins as lung cancer circulating biomarkers, we analyzed by ELISA assay matched plasma samples from 57 patients (TU) and 57 controls (CTR) for COL11A1 and COL10A1 and from 90 patients (TU) and 90 controls (CTR) for SPARC." (PMID 30227835, 2018). "The aim of the present study was to measure the levels of three circulating ECM related proteins (COL11A1, COL10A1 and SPARC) in plasma samples of lung cancer patients and in healthy heavy-smokers controls and test whether such measurements have diagnostic or prognostic value." (PMID 30227835, 2018).
pancreatic cancer (15 papers, 2010 to 2025). "Heightened expression of COL10A1 and its associated gene networks is correlated with poorer patient outcomes in both breast and pancreatic cancer." (PMID 39939916, 2025). "Survival analysis of pancreatic cancer patients suggested that high expression of COL10A1 was associated with a poorer prognosis and that knockdown of COL10A1 inhibited the proliferation, migration, and invasion of cells in functional assays." (PMID 41373732, 2025). "Expression of COL10A1 and its associated gene networks highlights inflammatory and immunosuppressive microenvironments, which identify aggressive breast and pancreatic tumors and contribute to metastatic potential in a sex-dependent manner." (PMID 39939916, 2025). "To identify possible roles and gene networks associated with COL10A1 in breast and pancreatic tumors, we used weighted gene co-expression network analysis (WGCNA) to generate cancer-specific ColX gene modules in the TCGA datasets for each cancer type." (PMID 39939916, 2025). "Previous papers have presented evidence indicating that COL10A1, a gene associated with an adverse prognosis, possesses a crucial involvement in pancreatic cancer progression and metastasis through its involvement in regulating collagen deposition." (PMID 39656597, 2024). "From this risk model, we can see that the upregulation of COL10A1/FAP/FN1 expression is a risk factor for pancreatic cancer, and the upregulation of all three increases the risk of developing PC in patients." (PMID 38063927, 2023). "Second, we found that COL10A1 was overexpressed in pancreatic cancer tissues and cell lines and associated with patient prognosis." (PMID 37974070, 2023). "COL10A1 is an early diagnostic marker, and its high expression correlates with immune infiltration in pancreatic cancer." (PMID 36105715, 2022). "In this study, we have demonstrated numerous links of biological and clinical interest between the stromal ECM in breast and pancreatic cancer as well as bone marrow and OA cartilage, highlighted by shared expression of COL10A1 and its associated gene networks." (PMID 39939916, 2025). "Collectively, the results of our study indicate that COL10A1 facilitates tumour progression by upregulating CD276 in pancreatic cancer." (PMID 37974070, 2023). "We tried to explore the role of COL10A1 in pancreatic cancer by analysing the data in a public database." (PMID 37974070, 2023). "According to the results, knockdown of COL10A1 repressed CD276 expression in pancreatic cancer cells." (PMID 37974070, 2023). "CCK-8, wound healing, and Transwell assays were used to study the role of COL10A1 in pancreatic cancer cell viability, migration, and invasion." (PMID 37974070, 2023). "The proliferation, invasion, and migration of pancreatic cancer cells were suppressed after COL10A1 knockdown in vitro." (PMID 37974070, 2023). "According to previous studies, most of the 10 identified hub genes have been studied in pancreatic cancer, with the exception of COL10A1." (PMID 37974070, 2023). "The role of COL10A1 in pancreatic cancer cell proliferation, migration, and invasion was investigated in vitro." (PMID 37974070, 2023). "Immune infiltration in pancreatic cancer correlates with high COL10A1 expression levels, with a new TUG1/miR-144-3p/COL10A1 axis identified upstream of the non-coding RNA pathway." (PMID 36765749, 2023). "Based on the expression levels of COL10A1/FAP/FN1, we further constructed a nomogram risk model for pancreatic cancer." (PMID 38063927, 2023). "The univariate analysis showed that COL10A1, histological grade, and pathological stage were important predictors of survival in pancreatic cancer patients." (PMID 36105715, 2022). "The TUG1/miR-144-3p/COL10A1 axis was identified as the most likely upstream noncoding RNA pathway for COL10A1 in pancreatic cancer." (PMID 36105715, 2022).
pancreatic cancer (continued). "After adjusting for tumor purity, COL10A1 expression levels were statistically related to 38 of the 55 pancreatic cancer immune cell markers." (PMID 36105715, 2022). "Combined with validation from multiple databases, the expression of COL10A1 in pancreatic cancer tissues was significantly higher than that in normal tissues." (PMID 36105715, 2022). "The clinical data of pancreatic cancer in TCGA were used to explore the relationship between COL10A1 and clinical features." (PMID 36105715, 2022). "High expression of COL10A1 was related to the clinicopathological characteristics and the worse prognosis of pancreatic cancer patients." (PMID 36105715, 2022). "COL10A1 was analyzed for correlation with immune cell infiltration and various immune checkpoint molecules in pancreatic cancer, and the possible mechanisms affecting the prognosis were also discussed." (PMID 36105715, 2022). "It was found that the expression of COL10A1 was significantly increased in pancreatic cancer tissues." (PMID 36105715, 2022). "We depicted a TUG1/miR-144-3p/COL10A1 axis to investigate the regulatory mechanism of COL10A1 in pancreatic cancer progression." (PMID 36105715, 2022). "COL10A1 was significantly elevated in a variety of cancers, including pancreatic cancer, compared with normal tissues." (PMID 36105715, 2022). "Among them, melanoma, pathway in cancer, basal cell carcinoma, bladder cancer, renal cell carcinoma and pancreatic cancer prove that COL10A1 affects the occurrence and development of cancer." (PMID 33371777, 2021). "Furthermore, COL10A1 expression was found to be elevated in pancreatic cancer tissues and cell lines (vs. corresponding controls) and to be inversely related to the prognosis of PAAD patients." (PMID 37974070, 2023). "COL10A1 expression in pancreatic cancer cell lines was measured by using qRT‒PCR." (PMID 37974070, 2023). "COL10A1 expression was also increased in pancreatic cancer cells vs. control cells." (PMID 37974070, 2023). "Interestingly, stage IIB resulted in an increased expression of genes encoding constituents of collagen X (COL10A1), collagen X1 (COL11A1), and collagen XII (COL12A1) isoforms, which have been reported to be prognostic markers of pancreatic cancer metastasis." (PMID 35565326, 2022). "In pancreatic cancer, COL10A1 was significantly negatively correlated with hsa-miR-144-3p only." (PMID 36105715, 2022). "Taken together, tumor immune infiltration may partially explain the oncogenic effect of COL10A1-mediated pancreatic cancer." (PMID 36105715, 2022). "Finally, COL10A1 was analyzed for correlation with immune cell infiltration and various immune checkpoint molecules in pancreatic cancer." (PMID 36105715, 2022). "The results showed that COL10A1 was significantly correlated with PD-L1 and CTLA-4 in pancreatic cancer, suggesting that COL10A1 may be associated with immune escape." (PMID 36105715, 2022). "We first analyzed the expression pattern and prognosis of COL10A1 in pancreatic cancer." (PMID 36105715, 2022). "In addition, a significant increase in COL10A1 expression was observed in pancreatic cancer cells." (PMID 37974070, 2023). "In addition, the lncRNA/miRNA/COL10A1 axis that may be involved in COL10A1 regulation in pancreatic cancer was explored by constructing a competitive endogenous RNA (ceRNA) regulatory axis." (PMID 36105715, 2022). "COL10A1 is thus a valuable biomarker for CAF-mediated ECM remodeling, immunosuppression, inflammation, and induction of invasion in breast and pancreatic tumors; future work will further elucidate its complex roles across diverse CAF and cancer types." (PMID 39939916, 2025). "The expression of five key genes (MMP11, COL10A1, SERPINE1, COL11A1, and EPYC) in normal pancreatic and pancreatic cancer cell lines were detected using qPCR." (PMID 38572434, 2024).
pancreatic cancer (continued). "Studies on COL10A1 in pancreatic cancer remain scarce, with only one relatively recent study mentioning that the COL10A1-DDR2 axis promotes the progression of pancreatic cancer by regulating MEK/ERK signaling." (PMID 38063927, 2023). "However, the role of COL10A1 in pancreatic cancer remains unclear." (PMID 37974070, 2023). "COL10A1 was transiently knocked down, while CD276 was transiently overexpressed in pancreatic cancer cells." (PMID 37974070, 2023). "Genes (n = 10) in cluster 2 were entirely labeled as activated stroma, containing periostin (POSTN), fibronectin 1 (FN1) and collagens (COL10A1, COL11A1), which have already been identified as deregulated in precursor lesions of pancreatic cancer." (PMID 29675033, 2018). "The best three single-gene discriminators are KRT17, COL10A1 and CTHRC1 for pancreatic cancer, having the same classification accuracy, 93.6% on the training set and 88.5% and 80.4%, 84.6% and 73.2%, and 84.6% and 85.7% on the two test sets, respectively." (PMID 21060876, 2010). "Moreover, COL10A1 was upregulated in the BxPC-3, Panc-1, and ASPC-1 pancreatic cancer cell lines compared with the human normal pancreatic duct epithelial cell line HPDE6-C7." (PMID 37974070, 2023). "In COVID-19 infected patients, COL10A1/FAP/FN1 are also significantly upregulated, and FN1 may promote the progression of pancreatic cancer through the PI3K-AKT signaling pathway." (PMID 38063927, 2023). "There were three proteins (COL10A1, DKK1, and TCN1) with no information in HPA; thus, it is not possible to report about the protein expression in pancreatic cancer." (PMID 32005189, 2020).
metaphyseal chondrodysplasia type Schmid (10 papers, 2014 to 2025). "Mutations in COL10A1, which is a specific marker of hypertrophic chondrocytes, result in Schmid metaphyseal chondrodysplasia (SMCD), an autosomal dominantly inherited skeletal disorder." (PMID 37082197, 2023). "Schmid-type metaphyseal chondrodysplasia (MCDS) is an autosomal dominant disorder caused by COL10A1 mutations, which is characterized by short stature, waddling gait, coxa vara and bowing of the long bones." (PMID 31856751, 2019). "Interestingly, mutations in COL10A1 result in metaphyseal chondrodysplasia type Schmid (MCDS, OMIM 156500), a form of dwarfism in which bone growth is disrupted." (PMID 37485234, 2023). "Metaphyseal chondrodysplasia type Schmid (MCDS), a rare skeletal disorder caused by COL10A1 mutations, exhibits significant phenotypic heterogeneity, yet genotype–phenotype correlations remain poorly defined." (PMID 41454937, 2025). "Pathological effects of signal peptide mutations have been characterized already in other genes (diseases) such as insulin (diabetes), COL10A1 (Schmid-type metaphyseal chondrodysplasia, MCDS), and COL5A1 (classical Ehlers–Danlos Syndrome, cEDS)." (PMID 29101475, 2018). "Mutations, mostly in the region of the COL10A1 gene encoding the C-terminal non-collagenous domain, cause the dwarfism metaphyseal chondrodysplasia type Schmid (MCDS)." (PMID 30010889, 2018).
breast tumor (7 papers, 2011 to 2023). "Of interest, increased expression of COL10A1 correlate with poor pathologic response in breast tumors." (PMID 32043519, 2020). "COL10A1 showed a relative expression level of 3937 in breast tumor tissues and only 21 in paracancerous breast tissues." (PMID 31182966, 2019). "Col10A1 mRNA expression is up-regulated in a variety of human malignancies compared to normal tissue, including breast tumors." (PMID 27090210, 2016). "COL10A1, COL1A1, and MFAP2 are constituents of the extracellular matrix remodeling, which is an important process in breast tumor invasion and tumor cell dissemination." (PMID 34149812, 2021). "Therefore, the protein product of the Col10A1 gene, colXα1 was a strong candidate to predict NAC response in ER+/HER2+ breast tumors and warranted further evaluation at the protein level based on the literature and these gene expression data." (PMID 27090210, 2016).
lung adenocarcinoma (7 papers, 2020 to 2025). A carcinoma that arises from the lung and is characterized by the presence of malignant glandular epithelial cells. "In general, COL10A1 was verified to be upregulated in lung adenocarcinoma and closely associated with lymphatic metastasis and poor prognosis in LUAD patients." (PMID 33324550, 2020). "A bioinformatics approach identified the type X collagen gene (COL10A1) as a gene with elevated expression in lung adenocarcinoma tissues and limited expression in normal tissues." (PMID 33324550, 2020). "In lung adenocarcinoma tissues, COL10A1 can originate not only from tumor cells, but also from fibroblasts." (PMID 33324550, 2020). "Correlation between expression of COL10A1 and the clinicopathological features of patients with lung adenocarcinoma." (PMID 33324550, 2020). "We constructed stable lung adenocarcinoma cell lines with overexpression or knockdown of COL10A1 via cell transfection experiments." (PMID 33324550, 2020). "The results addressed that COL10A1 is up-regulated and positively correlated with lymph node metastasis in lung adenocarcinoma, and the COL10A1 expression is also an independent prognostic factor." (PMID 33324550, 2020). "In our study, COL10A1 was dramatically upregulated in lung adenocarcinoma tissues compared with adjacent normal tissues, as confirmed by qRT-PCR and IHC." (PMID 33324550, 2020). "For instance, COL10A1 interacts with DDR2 to facilitate cancer cell proliferation and migration, enhancing the migration, invasion, and proliferation of lung adenocarcinoma." (PMID 40002743, 2025). "COL10A1, which was the brown module hub gene, is a component of the ECM that is known to facilitate lung adenocarcinoma metastasis." (PMID 36245556, 2022). "Moreover, epithelial cell transforming sequence 2 (ECT2)/FAK and collagen type X alpha 1(COL10A1)/discoid protein domain receptor 2 (DDR2)/FAK pathways contribute to the proliferation and adhesion on ECM of lung adenocarcinoma cells." (PMID 36906534, 2023). "As members of the collagen family, the origin cells and the special molecular mechanism of COL10A1 upregulation in lung adenocarcinoma are not yet clear, and further studies are required for confirmation." (PMID 33324550, 2020).
chondrodysplasia (6 papers, 2008 to 2023). "The main role of COL10A1 gene is to promote cartilage ossification, and diseases associated with COL10A1 include metaphyseal chondrodysplasia, schmid type, and cartilage disease." (PMID 33934516, 2021). "In a model of metaphyseal chondrodysplasia type Schmid, a chondrodysplasia characterized by short stature and ER stress in the growth plate because of Col10a1 mutations, mice exhibit short stature because of increased expression of Sox9 via ATF4 and CHOP transactivation." (PMID 37796615, 2023). "In addition to variants in COL1A1 and COL1A2 associated with OI, many pathogenic variants in COL2A1 and COL10A1 are linked to chondrodysplasias." (PMID 33672767, 2021). "The first hint that NMD efficiency could vary between tissues from the same individual came from the study by Bateman and colleagues on truncating mutations in the collagen X gene, COL10A1, responsible for Schmid metaphyseal chondrodysplasia (MIM 156500)." (PMID 19061508, 2008).